ST6GALNAC4 (ST6 N-acetylgalactosaminide alpha-2,6-sialyltransferase 4)
Description:
Transfers the sialyl group (N-acetyl-alpha-neuraminyl or NeuAc) from CMP-NeuAc to the GalNAc residue on the NeuAc-alpha-2,3-Gal-beta-1,3-GalNAc sequence of glycoproteins and glycolipids forming an alpha-2,6-linkage. Produces branched type disialyl structures by transfer of a sialyl group onto a GalNAc residue inside the backbone core chains. Prefers O-glycans to glycoproteins or glycolipids.
Synonyms: ST6GalNAcIV; SIAT3-C; SIAT7-D; SIAT3C; SIAT7D; IV; ST6GalNAc
Tractability: Antibody: UniProt predicts a signal peptide or a membrane-spanning region. PROTAC: ubiquitination databases record sites on it.
Gene: Protein-coding gene on chromosome 9 (127,907,876 to 127,917,055, reverse strand). Ensembl gene ENSG00000136840.
Subcellular location: Golgi apparatus membrane
Subcellular location (Human Protein Atlas): Golgi apparatus; Nucleoplasm
Pathways (Reactome):
Disease: Maturation of protein 3a; Maturation of spike protein
Metabolism of proteins: Sialic acid metabolism; Termination of O-glycan biosynthesis
Gene Ontology:
Molecular function: alpha-N-acetylgalactosaminide alpha-2,6-sialyltransferase activity; alpha-N-acetylneuraminyl-2,3-beta-galactosyl-1,3-N-acetyl-galactosaminide 6-alpha-sialyltransferase activity; sialyltransferase activity
Biological process: ganglioside biosynthetic process; glycolipid metabolic process; oligosaccharide metabolic process; protein O-linked glycosylation via N-acetyl-galactosamine; viral protein processing; glycoprotein biosynthetic process
Cellular component: Golgi membrane
Genetic constraint (gnomAD): Loss-of-function variants: 24 observed, 30.34 expected, observed/expected ratio (o/e) 0.79, 90% interval 0.57 to 1.11. The upper end of that interval is the gene's LOEUF score, 1.11, which puts it in group 4 of 6, group 1 being the genes least tolerant of losing a copy. Missense variants: 365 observed, 415.18 expected, observed/expected ratio (o/e) 0.88, 90% interval 0.81 to 0.96. Synonymous variants: 156 observed, 176.27 expected, observed/expected ratio (o/e) 0.89, 90% interval 0.78 to 1.01.
Homologues: Orthologues: chimpanzee ST6GALNAC4 (98% identical), macaque ST6GALNAC4 (98% identical), dog ST6GALNAC4 (92% identical), pig ST6GALNAC4 (91% identical), guinea pig ST6GALNAC4 (90% identical), mouse St6galnac4 (89% identical), rat St6galnac4 (88% identical), rabbit ST6GALNAC4 (77% identical), tropical clawed frog st6galnac4 (59% identical), zebrafish st6galnac4 (47% identical). Paralogues in human: ST6GALNAC3 (43% identical), ST6GALNAC5 (42% identical), ST6GALNAC6 (36% identical), ST3GAL1 (22% identical), ST3GAL2 (21% identical), ST6GAL2 (21% identical), ST6GALNAC1 (21% identical), ST6GALNAC2 (21% identical), ST6GAL1 (19% identical), ST3GAL4 (19% identical), ST3GAL5 (19% identical), ST3GAL3 (18% identical), and 2 more.
Diseases named in the same sentence as ST6GALNAC4 in open-access papers:
ST6GALNAC4 is named in the same sentence as 20 diseases in open-access papers, as found by Europe PMC text mining. Sharing a sentence is not in itself a finding about the gene and the disease. The quoted sentences say what the papers report.
breast carcinoma (4 papers, 2021 to 2022). "ST6GALNAC4 expression is related to glycosphingolipids synthesis, which has a connection with breast cancer." (PMID 34970268, 2021). "With respect to the O-GalNAc pathway, we observed alterations in several related glycogenes including the downregulation of GCNT4, GALNT13, GALNT16 and C1GALT1, and upregulation of ST3GAL1, ST6GALNAC4 and GAL3ST2 in Her2+ breast cancer tissue." (PMID 36282863, 2022). "Meanwhile, several other risk model genes were identified in this study (ST6GALNAC4, PLPP2, ELOVL1, HACD1, VAPB, CERS2, ALDH3B2, and HACD3) have not yet been explored in depth in breast cancer." (PMID 36059802, 2022).
hepatocellular carcinoma (4 papers, 2023 to 2025). A malignant tumor that arises from hepatocytes. "We knocked down st6galnac4 using shRNA in mouse hepatoma cell line (Hepa1-6)." (PMID 37381011, 2023).
follicular thyroid carcinoma (2 papers, 2022). "ST6GALNAC4 has attracted only a few works and has been reported to promote the invasive properties of human follicular thyroid carcinoma." (PMID 35444644, 2022). "miR-4299 mediated the invasive properties and tumorigenicity of human follicular thyroid carcinoma via targeting ST6GALNAC4." (PMID 35774357, 2022).
lung carcinoma (2 papers, 2022 to 2023). "Overexpression of ST6GalNAc4 has been crucial for tumor cell glycosylation modification and lung cancer metastasis, although the roles of ST6GalNAc5 and ST6GalNAc6 in malignancies remain unclear." (PMID 36605200, 2022).
acute coronary syndrome (1 paper, 2023). Signs and symptoms related to acute ischemia of the myocardium secondary to coronary artery disease. "A recent study found that patients with acute coronary syndrome had a lower expression of ST6GALNAC4." (PMID 37671094, 2023).
leukemia (1 paper, 2023). A malignant (clonal) hematologic disorder, involving hematopoietic stem cells and characterized by the presence of primitive or atypical myeloid or lymphoid cells in the bone marrow and the blood. "Importantly, upregulation of St6galnac4 is a core component of this glycogene signature and was preserved in both types of MYC-driven leukemia and lymphoma." (PMID 36897988, 2023).
cancer (8 papers, 2008 to 2025). A tumor composed of atypical neoplastic, often pleomorphic cells that invade other tissues. "Although the exact mechanisms by which ST6GalNAc4 contributes to BC progression are still under investigation, it is evident that this enzyme plays a significant role in cancer development and progression." (PMID 40443562, 2025). "Our study indicated that ST6GALNAC4 has a cancer-promoting role in HCC In vitro and in vivo functional warranting further mechanistic study." (PMID 37381011, 2023). "ST6GalNAc4 has been shown to promote cancer cell proliferation, migration, and invasion." (PMID 40443562, 2025).
tumor (8 papers, 2009 to 2025). "Next, we examined the effect of tumor-associated St6galnac4 expression on the host immune environment." (PMID 36897988, 2023). "Therefore, T-ALL associated St6galnac4, and thus disialyl-T, interferes with myeloid-mediated immunity and T cell activity to promote tumor development in vivo." (PMID 36897988, 2023). "First, St6galnac4 knockdown T-ALL exhibited reduced tumor growth when transplanted into immunocompetent, WT FVB/N mice intravenously and subcutaneously." (PMID 36897988, 2023). "GOLGA7, ITPK1, and ST6GALNAC4 genes had lower expression in tumor tissues than in healthy persons (p < 0.05) by means of Wilcoxon signed-rank test." (PMID 34970268, 2021). "As glycosylase-glycosylated antigens-lectin receptors axis plays unique immunoregulatory roles on the tumor microenvironment, we proposed a hypothesis that ST6GALNAC4 might exert immunosuppressive roles in HCC." (PMID 37381011, 2023). "We asked whether St6galnac4 and disialyl-T promote tumor growth in vitro and in vivo." (PMID 36897988, 2023). "We found the increased expression of PFKP, TPX2, UBE2S, ST6GALNAC4, ADAM15, G6PD, and KPNA2, but decreased expression of GOT2 in tumor samples compared to normal samples." (PMID 40307857, 2025). "The results showed that the expression levels of CORO1B, GOLGA7, PCSK4, ST6GALNAC4, and ZSWIM1 in normal tissues were significantly higher than those in tumor tissues, which were similar to the trends detected in the TCGA dataset." (PMID 34970268, 2021).
ST6GALNAC4 also shares sentences with these, for which no sentence is quoted: liver fibrosis (3 papers); type 2 diabetes (3); atherosclerosis (1); Creutzfeldt-Jakob disease (1); ganglioglioma (1); Hyperglycemia (1); infection (1); lipoma (1); lymphoma (1); memory impairment (1); renal fibrosis (1); Uterine leiomyoma (1).